RAD51C (RAD51 paralog C)
Diseases named in the same sentence as RAD51C in open-access papers (continued):
Sharing a sentence is not in itself a finding about the gene and the disease.
breast cancer (continued). "A subsequent study employing 456 breast cancer patients of varying subtypes validated that, in addition to BRCA1/2 status, high degrees of LST were correlated to RAD51C mutational status." (PMID 36077694, 2022). "BOADICEA was extended to further incorporate the associations of pathogenic variants in BARD1, RAD51C and RAD51D with breast cancer risk." (PMID 36162851, 2022). "In a The Cancer Genome Atlas (TCGA) cohort of 467 breast cancer patients, a significant association between the degree of LST and BRCA1/2 and RAD51C mutational status or expression levels was also found." (PMID 36077694, 2022). "Protein-truncating variants in RAD51C predispose to high-grade serous ovarian cancer (HGSOC) and triple-negative (TN) breast cancer (BC), and when these cancers occur in carriers of truncating variants they exhibit biallelic inactivation." (PMID 35039523, 2022). "Several reports also demonstrated the existence of other genes at medium and low penetrance (e.g., BRIP1, RAD51C, RAD51D, BARD1, and PALB2), which have been associated with both Breast Cancer (BC) and OC risk." (PMID 35053526, 2022). "Germline RAD51C pathologic variants have been linked with an increased risk of tubo-ovarian carcinoma (RAD51C mutant RR 7.55, 95% CI = 5.60–10.19) and breast cancer (RAD51C mutant RR 1.99, 95% CI = 1.39–2.85)." (PMID 35626165, 2022). "The chromosomal region, in which the RAD51C gene is located, has been found to be often amplified in sporadic breast cancers." (PMID 36293346, 2022). "At least eight genes were found to be significantly associated with breast cancer risk: BRCA1 (MIM#113705), BRCA2 (MIM#600185), ATM (MIM#607585), BARD1 (MIM #601593), CHEK2 (MIM#604373), PALB2 (MIM#610355), RAD51C (MIM#602774), and RAD51D (MIM#602954)." (PMID 36139699, 2022). "Our previous study showed that low frequencies of RAD51C (0.08%) and RAD51D mutations (0.73%) were identified in cohorts of breast cancers only." (PMID 35608067, 2022). "From breast cancer studies it is suggested that inactivation of RAD51C can lead to HRD, as cases with inactivation of RAD51C exhibited high levels of Signature 3, however the numbers were small (n = 2)." (PMID 36230674, 2022). "Germline variants in ATM, BRCA1, BRCA2, CHEK2, and PALB2 were associated with a high risk of breast cancer; a more modest risk was associated with BARD1 and RAD51C." (PMID 34445631, 2021). "In the NCCN Guidelines® Version 1.2022, it is stated that there are not sufficient data so far to suggest preventive management of breast cancer in carriers of GPVs of RAD51C or RAD51D (RAD51C/D)." (PMID 35008774, 2021). "A comparison cohort of breast cancers with expected HR defects from PALB2 (n = 15) and RAD51C (n = 9) germline LoF variant carriers, and 115 sporadic breast cancers sequenced using the same platform, were also evaluated." (PMID 33980861, 2021). "Studies of breast carcinoma have determined that reduced expression of HRR genes, such as BRCA1 and RAD51C, primarily via promoter methylation, associates with mutational signatures of HRRd." (PMID 34877933, 2021).
breast cancer (continued). "Studies on breast cancer have shown that epigenetic silencing of RAD51C and BRCA1 by promoter methylation is strongly associated with signature 3 and is highly enriched in basal-like breast cancers." (PMID 33324554, 2020). "Among them, CDKN2A showed a contribution to breast cancer risk that was comparable to that conferred by BRCA2, whereas RAD51C, RAD51D, BRIP1 were proven to be responsible for an increase in ovarian cancer risk." (PMID 31936873, 2020). "The germline mutation rate of the members of the Fanconi anemia gene family (including BRCA2, PALB2, and RAD51C) was 25.93% (7/27) among patients with germline mutations in TNBC, which was lower than those in unselected breast cancer." (PMID 33194720, 2020). "A recent study of multiple hereditary cancer genes identified both RAD51C [OR 1.84 (95% CI 1.28–2.71)] and RAD51D [OR 2.09 (95% CI 1.2–3.72)] as having an elevated risk of breast cancer." (PMID 33015624, 2020). "Mutations in other FA family members have been demonstrated to predispose to breast cancer, including PALB2 (FANCN), BRIP1 (FANCJ), RAD51C (FANCO), SLX4 (FANCP), and FANCM." (PMID 31320901, 2019). "Studies on TN breast cancer patients showed associations of breast cancer with mutations in moderate penetrance breast cancer susceptibility genes FALB2, BARD1, BRIP1, RAD51C, and RAD51D." (PMID 30249004, 2018). "Other potential sources of DNA repair deficiency in breast cancer, also involving DSB repair processes, include germline mutations in DNA repair genes PALB2, FANCM, ATM, CHEK2 (and possibly also RAD51C) characterized as loss-of-function variants." (PMID 28679371, 2017). "Here we have genotyped the CHEK2 mutations I157T and c.1100delC, the FANCM mutation p.Q1701X, the PALB2 mutation c.1592delT, the RAD51C mutations c.837+1G>A and c.93delG, and the RAD51D mutation c.576+1G>A in 68 male breast cancer patients." (PMID 28874143, 2017). "Recently, deleterious mutations in 14 known breast cancer susceptibility genes including BRCA1, BRCA2, and RAD51C were identified at a frequency of 3.7 % in a large series of 1,824 patients with TNBC unselected for family history of breast cancer." (PMID 27553291, 2016). "We extracted seven genes, XRCC3, XRCC2, RAD51C, RAD51L1, RAD51L3, FANCG, BRCA2, that formed a connected PPI network with eight interactions, and had been associated with breast cancer as well as other types." (PMID 24784581, 2014). "Biallelic mutations of some of these hereditary breast cancer susceptibility genes, namely BRCA2/FANCD1, BRIP1/FANCJ, PALB2/FANCN and RAD51C/FANCO, have been identified in patients with Fanconi anemia (FA, [MIM 227650])." (PMID 23840564, 2013). "Further confirmation of its role in breast tumors was the discovery that the MCF-7 breast cancer cell line contains a RAD51C-ATXN7 fusion gene consisting of RAD51C exons 1–7 and ATXN7 exons 6–13." (PMID 21980511, 2011). "Epigenetic silencing of BRCA2/RAD51C drives ~30% HRD in male breast cancer." (PMID 40864792, 2025). "This approach is particularly valuable when counseling individuals with variants in moderate-penetrance breast cancer genes like CHEK2, ATM, RAD51C, RAD51D, and BARD1, since the relative effect of risk factors is expected to be higher than in individuals with high-penetrance PVs." (PMID 40805171, 2025). "Deficiencies in the DNA damage repair pathway related genes constitute an important factor in the development of breast cancer, with approximately 10% of breast cancer cases being caused by mutations in HR genes, such as BRCA1, BRCA2, PALB2, BRIP1, BARD1, and RAD51C." (PMID 40830526, 2025).
breast cancer (continued). "No PGVs were seen in the breast cancer susceptibility genes RAD51C, RAD51D, or BARD1, all of which are known to be associated with triple-negative breast cancer, although not all patients had multigene panel tests including these genes." (PMID 39964682, 2025). "Given the rarity of RAD51C mutations, the risk of breast cancer after a diagnosis of EOC in RAD51C mutation carriers is not clear." (PMID 38360632, 2024). "Besides, rare variants in other genes like ATM, CHEK2, CDH1, PALB2, RAD50, and RAD51C have been detected mainly in the breast cancer subgroup." (PMID 39148954, 2024). "In the RADIOLA study, the RAD51-foci score is investigated if it has a predictive value on Olaparib efficacy in g/sBRCA or PALB2 or RAD51C/D mutation carrier advanced breast cancer patients; no results were posted." (PMID 38540206, 2024). "Furthermore, while recognition of RAD51C and RAD51D as OC predisposition genes has been established for several years, an association with breast cancer (BC) has only more recently been described and clinical management of this risk has been unclear." (PMID 36411032, 2023). "Of these, RAD51C duplication has previously been described, whereas the RAD52 delins and HSD17B14 deletion CNVs were characterized and investigated here for the first time for their association with breast cancer susceptibility." (PMID 37578974, 2023). "In addition, the genes that were tested in this study are not inclusive of all genes in which there are now data to support breast cancer risk association, including BARD1, RAD51C, and PTEN." (PMID 36544278, 2023). "The sensitivity of HRDetect for predicting BRCA1/2 mutation in the validation cohort was 86% in ER+/HER2- breast cancer patients and showed sensitivity to detect PALB2 biallelic inactivation or RAD51C hypermethylation, and to reclassify BRCA1/2 VUS as germline PV." (PMID 35158866, 2022). "Our study did not support RAD50, BRIP1 and RAD51C as breast cancer susceptibility genes in the Chinese population, consistent with results from case-control studies in Caucasian women." (PMID 34606182, 2021). "The identified breast cancer susceptibility genes in the FA pathway, including BRCA1, BRCA2, BRIP1, PALB2, and RAD51C, are essential genes involved in HR, the error-free pathway for DSB repair during physiological cell cycle progression, which repairs replication-associated DNA damage." (PMID 32300589, 2020). "Similarly to other genes such as BARD1, RAD51D, BRIP1, and RAD51C, FANCM is emerging as a breast cancer predisposing factor conferring a greater risk specifically for these breast cancer subtypes." (PMID 31991861, 2020). "Mutations in PALB2/FANCN increase breast and pancreatic cancer incidence, while truncating variants of BRIP1/FANCJ and RAD51C/FANCO increase ovarian but not breast cancer." (PMID 32962238, 2020). "Finally, among the breast cancer predisposition genes with moderate/high-penetrance, seven genes (BMPR1A, PTEN, CDH1, NF1, RAD51C, BRIP1, and CHEK2) were replicated for Korean BRCAX (eight for Asian and 15 genes for European high-risk breast cancers)." (PMID 30323354, 2018).
breast cancer (continued). "Cells that lack Rad51C, a Rad51 paralog, are reported to be highly sensitive to olaparib, and two murine breast cancer models have revealed that a pan-Class I PI3K inhibitor, BKM120, has the ability to inhibit Rad51, which was shown to lead to an increase in the anti-tumor effect of olaparib." (PMID 29152062, 2017). "Interestingly, monoallelic mutations in some of the downstream proteins are known to confer a high risk of breast cancer (e.g., FANCD1 = BRCA2, FANCN = PALPB2, FANCJ = BRIP1, FANCO = RAD51C)." (PMID 26567103, 2014). "However, genes of hot regions are linked to breast cancer disease such as BACH1, RAD51C, CYP24A1 and NCOA3." (PMID 23368971, 2013). "Heterozygous mutations in FA genes have been associated previously with increased breast cancer risk, and, conversely, bi-allelic mutations in breast cancer-associated genes BRCA2, BRIP1, PALB2, and RAD51C have been identified in persons with FA or FA–like syndromes." (PMID 23028381, 2012). "The mutation frequency observed in patients with unselected or hereditary breast cancer only was not significantly different from that observed in population controls, suggesting that mutations in RAD51C do not increase the risk of breast cancer per se." (PMID 22415235, 2012). "Other RAD51 gene family members had been associated with increased risk of breast cancer, but there had been no reports implicating RAD51C." (PMID 21980511, 2011). "Breast cancer (BC) risk is significantly associated with pathogenic variants in at least eight susceptibility genes: BRCA1 (MIM#113705), BRCA2 (MIM#600185), PALB2 (MIM#610355), ATM (MIM#607585), CHEK2 (MIM# 604373), BARD1 (MIM#601593), RAD51C (MIM#602774), and RAD51D (MIM#602954)." (PMID 41230741, 2026). "Among the 8 cases with RAD51C and RAD51D mutations, 6 (75%) were triple negative breast cancer, in agreement with the recent studies suggesting that mutations in these two genes may confer higher risks of triple-negative or basal subtypes of breast cancer." (PMID 29566657, 2018). "The breast cancer susceptibility and Fanconi proteins FANCD1/BRCA2, the partner of BRCA2 (PALB2/FANCN), a helicase associated with BRCA1 (FANCJ/BACH1), and several newly identified components including FAN1, FANCO/RAD51C, and FANCP/SLX4 participate in the pathway to respond to and repair DNA damage." (PMID 22693661, 2012). "In breast cancer, HRD in luminal and HR+/HER2- subtypes, and BRCA2/RAD51C hypermethylation in male breast cancer (~30% prevalence), warrant further trials." (PMID 40864792, 2025). "Nonetheless, other genes in the HRR pathway, such as the RAD51c, PALB2, BRIP1, and BARD1 gene defects, have also been shown to impact breast cancer progression and outcomes." (PMID 38397152, 2024). "For some genes, single P/LP variants were detected either only in the group of patients with breast cancer (APC, MDM1, MRE11, POLD1, NF1, RAD51C, RECQL4, and WRN) or only in the control group (MCPH1, MSH3, and XPC)." (PMID 39684352, 2024). "In ovarian and breast cancer, promoter methylation of BRCA1 or RAD51C is a promising biomarker for PARP inhibitor response, as high levels lead to homologous recombination deficiency (HRD)." (PMID 39055334, 2024). "Here, we performed whole-exome sequencing based analysis of rare CNVs in 98 hereditary breast cancer cases and identified recurrent alterations in RAD52, RAD51C and HSD17B14 genes." (PMID 37578974, 2023). "Amplification and overexpression of RAD51C, a paralog of RAD51, has been demonstrated in breast cancer cell lines including MCF-7 and a subset of primary breast cancer samples." (PMID 36428789, 2022).
breast cancer (continued). "In the case of ovarian and breast cancers, we limited our study to the subset of patients with available data for the methylation status of the BRCA1/RAD51C promoter." (PMID 35783256, 2022). "Amplification and overexpression of RAD51C (a paralog of RAD51) has also been demonstrated in breast cancer cell lines including MCF-7 and a subset of primary breast cancer samples." (PMID 36428789, 2022). "Somatic homozygous deletion, labeled as deep deletion, were observed in BRCA2 in a single breast cancer patient and in pancreatic cancer (RAD51B (n = 2), RAD51C (n = 2) and XRCC2 (n = 1))." (PMID 35783256, 2022). "However, several of our premenopausal breast cancer patients carried germline variants of unknown/uncertain significance (VUSs) in eight different breast cancer susceptibility genes, namely BRCA1, BRCA2, CHEK2, RAD51C, RAD51D, ATM, BRIP1, and PMS2." (PMID 36011273, 2022). "We found that, in different types of cells (A549-lung cancer, H1-human embryonic stem cells, HCT-116-colon cancer, MCF-7-breast cancer, SK-N-SH-neuroblastoma), TEAD4 directly binds to the promoter regions of RAD51C gene." (PMID 34488828, 2021). "More recently, RAD51C (a RAD51 paralog involved in double-strand break repair) and the RAD51 recombinase have been identified as targets of epigenetic silencing in breast cancer." (PMID 28679371, 2017). "In breast cancer, this catalogue includes CpG promoter methylation of BRCA1, RAD51C, FOXC1, RUNX3 and L3MBTL4." (PMID 28679371, 2017). "The detection of the Rad51C and ATXN7 fusion gene in the MCF-7 breast cancer cell line is intriguing." (PMID 27296891, 2016). "Next generation sequencing data have previously shown a fusion gene formed between Rad51C and ATXN7 genes in the MCF7 breast cancer cell line." (PMID 27296891, 2016). "In male breast cancer, HRD prevalence is ~30%, driven by epigenetic silencing of BRCA2 and RAD51C." (PMID 40864792, 2025). "HRD extends beyond BRCA1/BRCA2 mutations to include non-BRCA genes (RAD51C/RAD51D, BRIP1, BARD1, ATM, PALB2), broadening actionable targets across ovarian and breast cancer subtypes, including HER2-positive (30–40%) and luminal subtypes (15–25%)." (PMID 40864792, 2025). "In male breast cancer, BRCA2/RAD51C hypermethylation in ~30% of cases suggests PARPi potential." (PMID 40864792, 2025). "Using the breast cancer study as an example, it was found that the known eight famous genes—BRCA1, BRCA2, PALB2, BARD1, RAD51C, RAD51D, and ATM—in breast cancer research and practice actually lead to very low accuracy in predicting breast cancer status at the stage of diagnosis." (PMID 36298522, 2022). "BARD1, RAD51C and RAD51D explain 0.31% of the breast cancer polygenic variance." (PMID 36162851, 2022). "Given the relatively low frequency of RAD51C, RAD51D, FANCM, and PALB2 mutations among unselected female breast cancer patients, the absence of the studied mutations in the MBC series was not unexpected." (PMID 28874143, 2017). "In this study, we did not detect the RAD51C, RAD51D, FANCM, or PALB2 mutations among male breast cancer patients." (PMID 28874143, 2017). "However, no consensus was reached for recontact regarding breast cancer risk management in intermediate penetrance CSGs (ATM, CHEK2, RAD51C, RAD51D or BARD1)." (PMID 41159931, 2025). "Similarly, Li et al22 found that 2 ER-positive cases out of 9 cases of breast cancer retained heterozygosity across the RAD51C locus and were the only cases of breast cancer that did not exhibit HRD." (PMID 38648056, 2024).